NFE2L2 (NFE2 like bZIP transcription factor 2)
Diseases named in the same sentence as NFE2L2 in open-access papers (continued):
Sharing a sentence is not in itself a finding about the gene and the disease.
hepatocellular carcinoma (43 papers, 2015 to 2025). A malignant tumor that arises from hepatocytes. "In this line, next-generation sequencing of the cancer genome identified that oxidative stress-related transcription factor NRF2 (NFE2L2) is mutated in different cancers, including hepatocellular carcinoma (HCC)." (PMID 34069882, 2021). "In hepatoma cells, treatment with erastin or sorafenib increases NFE2L2 protein levels in both nuclear and whole cell extracts, as well as NFE2L2 transcriptional activity and NFE2L2 cofactor binding." (PMID 39025451, 2024). "NFE2L2 knockdown or gene disruption also sensitizes lung adenocarcinoma cells, hepatoma cells, rat and human glioma cells, and ovarian cancer cells to ferroptosis." (PMID 39025451, 2024). "For example, silencing the NFE2L2 gene increased 5FU sensitization in hepatocellular carcinoma cells, RTN4 knockdown promoted higher cytotoxic events in paclitaxel-treated cancer cells, and RND3 overexpression promoted drug resistance in gastric cell lines." (PMID 36675023, 2023). "Overexpressing NBR1 promotes SQSTM1 accumulation and phosphorylation in liquid-like bodies and SQSTM1-mediated activation of NFE2L2/NRF2 provides hepatocellular carcinoma cells proliferation potency." (PMID 34829881, 2021). "ATG7 and NFE2L2 are downregulated by apigenin and directly targeted by miR-520b and miR-101, respectively, in hepatocellular carcinoma." (PMID 33066509, 2020). "NFE2L2 transcriptional activity plotted by lineage revealed the highest overall activity in hepatocellular carcinoma (HCC) and biliary cancer." (PMID 27109210, 2016). "Moreover, it was demonstrated that 10 and 50 μM TBBPA increased NFE2L2 protein levels in the human hepatoma Hep3B cell line, which, according to these authors, indicated the mechanism of antioxidant enzyme expression control." (PMID 37213006, 2023). "Whereas one report noted Nfe2l2 activation via promoter hypomethylation in mouse skin epidermal cells, another showed miRNA-mediated inhibition of human NFE2L2 by apigenin, leading to chemosensitization of adriamycin-resistant hepatocellular carcinoma cells." (PMID 32938017, 2020). "Clearly, the aberrant (and/or mutant) activation of Keap1-Nrf2 and Wnt/β-catenin signaling cascades is a genetic predisposition to hepatocellular carcinoma, in which the CTNNB1 mutation appeared to occur earlier during child liver carcinogenesis, whereas the NFE2L2 mutation was acquired later." (PMID 32273945, 2020). "A study of the drug resistance mechanism of sorafenib in hepatocellular carcinoma (HCC) cells discovered the first evidence that NFE2L2 inhibits ferroptosis." (PMID 38274225, 2023). "Interestingly, the NFE2L2 missense variant c.246A > C identified in sample 193_T, is annotated in the catalogue of somatic mutation in cancer (COSMIC database, COSV67960116) as pathogenic in different cancer types including lung adenocarcinoma, renal cell carcinoma and liver carcinoma." (PMID 39707614, 2025). "In hepatoma cells, erastin induces NQO1 expression in an NFE2L2-dependent manner, and knocking down NQO1 enhances erastin-induced growth arrest." (PMID 39025451, 2024). "In multiple previous studies, somatic mutations of NFE2L2, the homolog of NFE2L3, was detected in plasma cell-free DNA (cfDNA) in hepatocellular carcinoma (HCC) and lung squamous cell carcinoma (LUSC), and was regarded as a non-invasive biomarker for tumor risk prediction and overall survival." (PMID 35664314, 2022). "Apigenin has been proven to sensitize hepatocellular carcinoma through downregulating the levels of autophagy-related 7 (ATG7) and nuclear factor erythroid 2-related factor 2 (NFE2L2, also known as NRF2)." (PMID 33066509, 2020). "Since low SOCS1 gene expression correlates with poor prognosis in the TCGA-liver hepatocellular carcinoma (LIHC) dataset, and high GCLC in HCC tissues correlates with poor prognosis, we evaluated the relationship between SOCS1, NFE2L2 (NRF2) and GCLC gene expression in the TCGA-LIHC dataset." (PMID 38254783, 2024).
hepatocellular carcinoma (continued). "NFE2L2 generally functions as a master negative regulator of ferroptosis, because activation of the SQSTM1–KEAP1–NFE2L2 pathway is an important homeostasis mechanism to block ferroptosis in hepatocellular carcinoma (HCC) induced by sorafenib." (PMID 33574983, 2021). "It is less clear whether or how NFE2L2 influences FTL expression, as NFE2L2 does not seem to regulate FTL mRNA levels in hepatoma cells and negatively regulates FTL mRNA and protein levels in human cells and in mice." (PMID 39025451, 2024).
glioma (35 papers, 2015 to 2026). A benign or malignant brain and spinal cord tumor that arises from glial cells (astrocytes, oligodendrocytes, ependymal cells). "NFE2L2 is a transcription factor which protects cells from the oxidative damage and is associated with resistance to cancer treatments, which was indicated as a prognostic indicator in gliomas." (PMID 36856182, 2023). "TCGA database analysis further revealed a strong positive correlation between NFE2L2 (the gene encoding NRF2) and CD44, TNFRSF1A, and ANXA1 expression in glioma tissues." (PMID 40583858, 2025). "Our findings indicated that NFE2L1 is predominantly expressed in glioma tumor tissues, with NFE2L2 exhibiting lower expression levels, whereas NFE2L3 was expressed at minimal levels." (PMID 40677211, 2025). "Targeted modulation of NFE2L2 and its downstream genes in gliomas has been shown to induce ferroptosis." (PMID 38685674, 2024). "NFE2L2 is the hub gene involved in m6A‐related ferroptosis in gliomas, which is strongly correlated with METTL16." (PMID 39248438, 2024). "Third, the correlation of NFE2L2 with immune checkpoints in low‐grade gliomas should be explored to elucidate the exact mechanism." (PMID 39248438, 2024). "In the UALCAN database, both METTL16 and NFE2L2 were found significantly upregulated in glioma tissues." (PMID 39248438, 2024). "Our experimental data demonstrated that glioma cell lines H4 and T98G exhibited higher expression levels of NFE2L2 compared to normal human astrocytes (NHAs)." (PMID 38819225, 2024). "In experiments, we validated that depleting glutathione (GSH), either through the application of the chemical inhibitor BSO or by knocking down its regulatory gene NFE2L2, negatively impacted glioma cell proliferation, colony formation, and migration." (PMID 38819225, 2024). "We also explored the perturbation effects of these genes which suggested that the importance of DPEP1, G6PD, GGT1, GGT5, IDH1, and NFE2L2 for glioma cell survival." (PMID 38819225, 2024). "To further explore the correlations of METTL16 and NFE2L2 with the immune microenvironment in gliomas, we compared the abundances of 22 types of tumour‐infiltrating immune cells between low‐grade glioma and normal tissues using the CIBERSORT R script." (PMID 39248438, 2024). "For example, Slc7a11 overexpression only partially reverts the sensitization to erastin observed in rat glioma cells in which Nfe2l2 has been knocked down." (PMID 39025451, 2024). "The expression of NFE2L2 increases with the histological severity of glioma, and NOX4 is also significantly increased in the gradeIV glioblastoma." (PMID 36627482, 2023). "Then, the Human Protein Atlas (HPA) database analysis also shows that KEAP1 and NFE2L2 expression is significantly higher in glioma tissues compared to normal tissues." (PMID 36627482, 2023). "In conclusion, the eccentric expression and appearance of NFE2L2 and NOX4 are risk factors in glioma." (PMID 36627482, 2023). "Our results verify that KEAP1 and NFE2L2 display clearly higher expression in glioma (GBM and LGG) tissues than in adjacent normal tissues." (PMID 36627482, 2023). "The cumulative survival of glioma patients with low NFE2L2 or NOX4 expression was significantly longer than that of glioma patients with high expression." (PMID 36627482, 2023). "There were 5 ferroptosis-associated genes (KEAP1, NFE2L2, NOX4, ATF4, ASCL4) that have been tested in human glioma with different research methods." (PMID 36627482, 2023). "Our findings suggested that the ferroptosis-associated genes NFE2L2 and NOX4 are potential risk prognostic biomarkers and are correlated with immune infiltration in glioma." (PMID 36627482, 2023). "The expression of GLS (p < 0.001), LIPT1, FDX1, SLC31A1 (p < 0.01), DLST, CDKN2A, PDHA1, ATP7A, ATP7B, and NFE2L2 (p < 0.05) was different between glioma and adjacent tissues." (PMID 36936439, 2023). "Recently, the NFE2L2 mRNA level has been shown to correlate with poor prognosis in patients with low-grade glioma." (PMID 36231068, 2022).
glioma (continued). "NFE2L2 is reported to be a prospective biomarker for prognosis and is shown to be related with immune infiltration in brain lower-grade glioma." (PMID 34531924, 2021). "Further studies reveal that HACE1 causes enhanced malignant phenotypes and decreased radiosensitivity of glioma cells by activating nuclear factor erythroid 2-related factor 2 (NFE2L2, also known as NRF2) via multiple mechanisms." (PMID 34815381, 2021). "The higher variability in CAT and NFE2L2 expression was observed in glioma biopsies, which also had the highest expression levels." (PMID 33540681, 2021). "And, although there was a lot of variability between glioma biopsies, it should be noted that there were two patients who had an NFE2L2 expression much higher than that observed in Hs766T cell line." (PMID 33540681, 2021). "One important relationship between the nuclear factor Nrf2 (NFE2L2) and mTOR has been pointed out to explain the complex role of ROS in gliomas." (PMID 33540681, 2021). "The expression of NFE2L2 has been shown to positively correlate with the expression of immune checkpoint markers in brain lower grade glioma." (PMID 34249910, 2021). "EZH2, NFE2L2, REST, SMAD4 and SUZ12 were all implicated as common transcriptional regulators of DEGs in glioma, sarcoma, breast and stomach cancers, suggesting that altered AMPK signaling converged on similar groups of transcriptional targets." (PMID 32807122, 2020). "NFE2L2 expression was significantly upregulated with increasing glioma grade." (PMID 38819225, 2024). "However, until now, there have been few studies on the role and mechanism of m6A in regulating NFE2L2 in glioma, and their potential regulatory effects await further investigation." (PMID 39248438, 2024). "In conclusion, these results indicate that NFE2L2 and NOX4 could be risk prognosis biomarkers in glioma, and they bound up with immune infiltration and tumor immunity in tumorigenesis." (PMID 36627482, 2023). "Furthermore, we analyzed the correlation of 1, 3, and 5-year cumulative survival rates of glioma patients with NFE2L2 and NOX4 expression." (PMID 36627482, 2023). "All results revealed that NFE2L2 and NOX4 appeared to be risk factors in glioma." (PMID 36627482, 2023). "Increasing evidence indicates that NFE2L2, a protein that is homologous to the NFE2L3 transcription factor, is involved in immune evasion and is associated with immune infiltration of low-grade gliomas." (PMID 34783304, 2021). "The tumor-promoting activity of NFE2L2 has been attributed to its own function; its activity is generally enhanced in glioblastoma cell lines and tumors, and low NFE2L2 expression inhibits proliferation and self-renewal of glioma stem cells." (PMID 33194668, 2020). "Although no mutations in KEAP1 or NFE2L2 have been reported in tumours of the central nervous system, NRF2 is hyperactivated in a subset of glioma patients, whose tumours display a mesenchymal subtype." (PMID 33276631, 2020). "Hence, overexpressed NFE2L2 in low‐grade gliomas may stimulate cancer progression by increasing the infiltration of M2 macrophages." (PMID 39248438, 2024). "Consequently, orexin‐A may induce ferroptosis in gliomas by selectively targeting NFE2L2 and regulating the downstream expression of GPX4, TFRC and FTH1." (PMID 38685674, 2024). "Therefore, NFE2L2 and NOX4 may function as a risk prognosis biomarker for glioma and play a vital role in immune infiltration and tumor immunity." (PMID 36627482, 2023). "In addition, we revealed the involvement of transcription factors UBTF and NFE2L2, which, to the best of our knowledge, have not been previously associated with the formation of aggressive forms, invasion, and metastasis of gliomas." (PMID 36231068, 2022). "Both of NFE2L2 and METTL16 are involved in the immune response of low‐grade gliomas, serving as novel therapeutic targets for gliomas." (PMID 39248438, 2024).
glioma (continued). "NFE2L2 is strongly correlated with METTL16, both of which play critical roles in the immune response of low‐grade gliomas." (PMID 39248438, 2024). "More importantly, we observed that NFE2L2 and NOX4 expression have a prognostic value in glioma with AUCs of 0.929 and 0.813, respectively." (PMID 36627482, 2023). "This indicates that the NFE2L2 and NOX4 expression-based signatures can better predict the prognosis of glioma." (PMID 36627482, 2023). "Survival curve and prognostic analysis showed that the overexpression of NFE2L2 and NOX4, respectively, has a remarkable link with a worse prognosis in glioma." (PMID 36627482, 2023). "Our analysis proved that low NFE2L2 and NOX4 expression in glioma patients from the TCGA database were significantly related to better pathologic stage and histological grade." (PMID 36627482, 2023). "This means that the expression levels of NFE2L2 and NOX4 would increase with the glioma development." (PMID 36627482, 2023). "It was observed that NS formation is accompanied by the activation of five common gliomas of TFs, SOX2, UBTF, NFE2L2, TCF3 and STAT3." (PMID 36231068, 2022). "MAPK3 and CX3CL1 were strongly positive; NFE2L2, HSP90AB1, and SUPT20H were moderately positive; and FKBP1B, BIRC5, NPC1, IKBKE, BID, and PTEN were weakly positive in glioma tissue relative to their expression levels in normal tissue." (PMID 33194668, 2020). "NFE2L2 interacted with METTL16 to regulate the immune response in low‐grade gliomas, and both molecules may be novel therapeutic targets for gliomas." (PMID 39248438, 2024). "In addition, the high expression of NFE2L2 or NOX4 was in an immunosuppressive state, and it correlated with tumor immunity in glioma." (PMID 36627482, 2023). "Besides, the expression of NFE2L2 and NOX4 was positively correlated with the WHO grade of glioma." (PMID 36627482, 2023). "Finally, in rat glioma cells, Nfe2l2 overexpression confers resistance to RSL3, but not erastin." (PMID 39025451, 2024).
Parkinson disease (30 papers, 2008 to 2025). A progressive degenerative disorder of the central nervous system characterized by loss of dopamine producing neurons in the substantia nigra and the presence of Lewy bodies in the substantia nigra and locus coeruleus. "In neurological disease, genetic variation in NFE2L2 has been associated with Parkinson's disease and amyotrophic lateral sclerosis incidence and age of onset." (PMID 36148820, 2023). "Based on previous NFE2L2 haplotype associations with Parkinson’s disease, five NFE2L2 tag SNPs were genotyped by allelic discrimination and three functional NFE2L2 promoter SNPs were genotyped by sequencing." (PMID 25496089, 2014). "Previous studies have shown that brain cells other than neurons cooperate to regulate oxidative stress responses in Parkinson’s disease-associated neurodegeneration and are able to provide “clue” signals that in turn induce the NFE2L2 pathway in neuronal cells." (PMID 34551802, 2021). "Stroke and traumatic brain injury have been reported to have a worse outcome in Nfe2l2-deficient mice due to increased oxidative stress and disorders like amyotrophic lateral sclerosis, Alzheimer’s disease and Parkinson’s disease have also been linked to reduced NRF2 levels." (PMID 29018201, 2017). "We hypothesized that decreased function of the nuclear factor (erythroid-derived 2)-like 2 (NFE2L2)-antioxidant response element (ARE) pathway might predispose to Parkinsonism." (PMID 26887053, 2016). "In conclusion, our study presents the evidence of a strong association between functional polymorphisms of NFE2L2 gene and the risk of Parkinson's disease in Chinese populations, suggesting a critical role of NFE2L2 in ROS activity in the development of Parkinson's disease." (PMID 26887053, 2016). "Our results support the hypothesis that variation in the NFE2L2 gene, encoding a central protein in the cellular protection against oxidative stress, may contribute to the pathogenesis of Parkinson’s disease." (PMID 25496089, 2014). "Many studies have implicated Nrf2 (Nfe2l2) in cancer or inflammation-associated diseases such as colitis, and Parkinson's disease, and NF-κB in inflammation and cancer." (PMID 19050705, 2008). "Additionally, abnormal expression or dysfunction of NFE2L2 has been implicated in the development of various diseases, including cancer, neurodegenerative diseases (such as Alzheimer’s disease and Parkinson’s disease), cardiovascular diseases, and inflammatory disorders." (PMID 37946105, 2023). "Therefore, genetic variants of NFE2L2 may be directly linked to reduced target gene expression in Parkinson's disease." (PMID 26887053, 2016). "Therefore, it is possible that Parkinson's disease associated NFE2L2 variation might be involved in dysregulated NFE2L2-Keap1 biological cascade and antioxidant response pathway." (PMID 26887053, 2016). "In their research, von Otter with colleagues studied promotor haplotypes (rs35652124 T/rs6706649 C/rs6721961 G) of the NFE2L2 gene in Swedish and Polish cohorts of patients with Parkinson’s disease." (PMID 36980990, 2023). "Accumulation of damage due to the continuous impairment of NFE2L2 signaling is consistent with the constant low levels of neuronal death occurring during the long process of Parkinson’s pathogenesis, starting years before the onset of clinical manifestations." (PMID 34551802, 2021). "Future investigation is warranted to elucidate the detailed mechanisms of antioxidant signaling pathways in Parkinson's disease and to develop possible interventions targeting NFE2L2-ARE pathways for neurodegenerative disease therapy." (PMID 26887053, 2016). "For example, this would hold true for Nfe2l2 (Nrf2) and Park7 (Parkinson disease (autosomal recessive, early onset) genes as joint regulators of a common target gene." (PMID 18769717, 2008).
Parkinson disease (continued). "Here, we hypothesize that variation in NFE2L2 and KEAP1, the genes encoding the two major regulators of the phase II response, may affect the risk of Parkinson's disease." (PMID 20196834, 2010). "The alternate T allele has been associated with later age of onset in Parkinson's disease, although the effect of the genetic variant is unknown, with no change in expression of NFE2L2 in human olfactory neurosphere‐derived cell lines." (PMID 36148820, 2023). "Meta-analyses of NFE2L2 haplotypes showed association of haplotype GAGCAAAA, including the fully functional promoter haplotype AGC, with decreased risk (OR = 0.8 per allele, p = 0.012) and delayed onset (+1.1 years per allele, p = 0.048) of Parkinson’s disease." (PMID 25496089, 2014). "These include genes in the pathways for amyotrophic lateral sclerosis (NEF3, NEFL, NEFH), Huntington's disease (CALM3, CLTC, CLTB), neurodegenerative disorders (APLP1, NEFH, FBXW7), Parkinson's disease (GPR37) and prion disease (APLP1, NFE2L2)." (PMID 19948073, 2009).